CCNA2 (cyclin A2)
Diseases named in the same sentence as CCNA2 in open-access papers (continued):
Sharing a sentence is not in itself a finding about the gene and the disease.
tumor (continued). "Finally, the expressions of miR-23b and miR-130b, which target HMGA2 and CCNA2 genes, have been reported as down-regulated in somatotroph, gonadotroph, and silent PitNETs, while miR-183, which targets KIAA0101, appears to be down-regulated in aggressive lactotroph tumours." (PMID 32316225, 2020). "Moreover, the mRNA of several cell cycle regulatory genes, such as Cdc25b, Cyclin B1, Cyclin A2, Plk1, Cks1, Aurora B, and Topo 2 alpha were decreased in prostates of TRAMP/SPDEF OE mice, a finding consistent with decreased cellular proliferation and decreased tumor sizes." (PMID 25254494, 2014). "There was a significant negative correlation between CCNA2 expression and miR-219-5p expression in ESCC tumor samples (p = 0.0357, r = − 0.4718)." (PMID 30766610, 2019). "We showed that CCNA2 was highly expressed along with the pronounced downregulation of FXR and miR-22 in a considerable proportion of the tumor tissues in comparison to noncancerous ones." (PMID 27738335, 2016). "Therefore, CBX8, c-Myc and cyclin A2 are most likely not good therapeutic targets; however, they are able to promote proliferation even while their inhibition may enhance metastasis, indicating that current strategies mainly targeting proliferation may have undesirable effects on tumor progression." (PMID 25360999, 2014).
cancer (328 papers, 1997 to 2026). A tumor composed of atypical neoplastic, often pleomorphic cells that invade other tissues. "It clearly showed that amplification is the most common alteration observed in BOP1, PLAU, SERPINE1, and CKS2 across the cancers, whereas in CCNA2, mutation and deep deletion are prevalent." (PMID 36203433, 2022). "We chose the cancer types in which high CCNA2 expression is associated with poor OS by the Kaplan–Meier survival curve and log-rank test simultaneously." (PMID 35480884, 2022). "Further study is required to clarify the detailed mechanism underlying the role of CCNA2 in impacting those signaling pathways in cancers and ccRCC." (PMID 35401923, 2022). "CCNA2 encodes Cyclin A2 which functions as a cell cycle regulator and its expression is elevated in many human cancers." (PMID 34172056, 2021). "The expression level of the cell cycle regulators (i.e. CCNT2 and CCNA2) has been linked to cell cycle progression and cancer growth." (PMID 30944375, 2019). "Moreover, CCNA2 has been associated with cancer aggressiveness, recurrence, metastasis, and chemoresistance in many kinds of cancer." (PMID 38895552, 2024). "Furthermore, CCNA2 is positively associated with expressions of immune checkpoints in most cancer types." (PMID 35480884, 2022). "CCNB1, CCNB2, and CCNA2 are the authorizing members of the cyclin family, critical for regulation of cellular growth, proliferation, and apoptosis; and consequently, associated with cancer development and progression." (PMID 32752229, 2020). "CCNA2 is also associated with epithelial-mesenchymal transition and cancer progression." (PMID 32411535, 2020). "Its expression levels have been shown to be significantly lower in various human cancers, indicating that reduced expression of CCNA2 may be associated with cancer development and growth." (PMID 30766610, 2019). "Cyclin A2 expression is associated with a poor prognosis in several types of cancer." (PMID 28049433, 2017). "Since SKP2 and CCNA2 are known to be implicated in the pathogenesis of various cancers as oncogenes, the effects of each TIA1 protein isoform on the SKP2 and CCNA2 protein levels were investigated using cells transiently expressing each isoform via retroviral infection." (PMID 26958940, 2016). "In addition, over-expression of cyclin A2 in cancers is associated with enhanced cellular proliferation and predicted a poor prognosis." (PMID 26378658, 2015). "Notably, CCNA2 has been associated with aberrant cell cycle progression in several types of cancer, and has been posited as a potential therapeutic target that could be inhibited to repress cell proliferation." (PMID 37077524, 2023). "The identification of CCNA2, CHK1, CHK2, E2F1, and TOP2A as core genes in HCC is consistent with previous research that has linked these genes to cancer progression." (PMID 40573296, 2025). "Another interesting target showing higher basal expression in gas plasma and H2O2-sensitive cell lines was cyclin A2 (CCNA2), which regulates the cell cycle by binding cyclin-dependent kinases and is regarded as a prognostic marker of different cancer types." (PMID 39858101, 2025). "Four key genes CCL2, CCR7, LY96, and PTPRC, from ClusterK1 and five genes AURKA, CDK1, CCNA2, FEN1, and PLK1 from ClusterK2, were associated with at least one type of cancer." (PMID 38872418, 2024). "For example, a biosensing platform was generated of porphyrinnon- functionalized graphene-modified glassy carbon electrode for clinical diagnosis of cyclin A2 which is a prognostic indicator in early-stage cancers." (PMID 38956651, 2024). "CCNA2, one of the highly conserved cyclin family, was significantly overexpressed in some cancer cells and had a close relation with tumorigenesis and progression." (PMID 37064084, 2023).
cancer (continued). "CCNA2 is found to promote uncontrolled cell growth, resulting in tumorigenesis in the case of different cancer types." (PMID 36900109, 2023). "Our analysis shows that CCNA2 is an important gene in the cell cycle, and it is significantly upregulated in many cancer types." (PMID 35186743, 2022). "Taken together, our first pan-cancer analysis of CCNA2 indicated its overexpression is widespread in different cancer types." (PMID 35480884, 2022). "Our first CCNA2 pan-cancer study contributes to understanding the prognostic and immunological roles and potential upstream molecular mechanisms of CCNA2 in different cancers." (PMID 35480884, 2022). "The disorder of CCNA2 contributes to multiple cancers, implying its potential role in cancer diagnosis and prognosis." (PMID 35186743, 2022). "We separated the cancer cases into high-expression groups (50%) and low-expression groups (50%) according to the expression levels of CCNA2." (PMID 35480884, 2022). "We also employed the “Pathological Stage Plot” module of GEPIA2 to observe the correlation between CCNA2 expression and the pathological stages of cancers." (PMID 35480884, 2022). "CCNA2 is over-expressed in a variety of human malignancies, suggesting its potential role in cancer transformation and progression." (PMID 35906548, 2022). "In the TCGA project, we used the “Survival Plots” module of GEPIA to analyze the relationship between CCNA2 expression level and the clinical prognosis of patients with different cancer types." (PMID 35480884, 2022). "The relationship between four methyltransferases was analyzed, and the results showed that the expression level of CCNA2 was positively correlated with all four methyltransferases in 23 cancer types." (PMID 35401923, 2022). "For the first time, our research uses the TCGA project to investigate a pan-cancer analysis of CCNA2, including gene expression, clinical survival prognosis, pathological stage, immune cell infiltration, immune cell markers, and immune checkpoints." (PMID 35480884, 2022). "CCNA2 contributed to the cell cycle pathway, and it also had a role in the hallmarks of cancer in reprogramming energy metabolism." (PMID 35186743, 2022). "Overall, the correlation of the CCNA2 expression with immune infiltration level in diverse cancer types is different." (PMID 35480884, 2022). "Further in-depth analysis characterized CCNA2/MKI67/KIF11:miR-30a-5p:VPS9D1-AS1 axis-related cell cycle as a prognostic biomarker, and all of these RNAs were cancer-associated crucial genes." (PMID 35186743, 2022). "Our results indicated that CCNA2 is significantly related to the occurrence and progresses of various cancer types." (PMID 35401923, 2022). "We first analyzed the CCNA2 expression in cancer types with five or more adjacent normal tissues from the TCGA project." (PMID 35480884, 2022). "Integrations occurred in the known cancer driver genes CCNA2, (four cases), TERT (one case), CCNE1 (three cases), TNFSF10 (two cases) and KMT2B (one case), leading to overexpression of the target genes." (PMID 36316711, 2022). "Overexpression of CCNA2 is widespread in almost all cancer types, and it is related to poor prognosis and advanced pathological stages in most cases." (PMID 35480884, 2022). "For the first time, we analyzed potential oncogenic roles of CCNA2 in 33 cancer types via The Cancer Genome Atlas (TCGA) database." (PMID 35480884, 2022). "CCNA2 interacts with many other differentially expressed proteins, indicating its essential role in many cancers." (PMID 35480884, 2022). "Our work of CCNA2 pan-analysis contributes to understanding the prognostic and immunological roles and potential upstream molecular mechanisms of CCNA2 in different cancers." (PMID 35480884, 2022). "Overall, CCNA2 is generally positively correlated with expressions of these immune checkpoints in most cancer types." (PMID 35480884, 2022).
cancer (continued). "After including the normal tissues from the GTEx project as controls, we determined the expression level of CCNA2 in other cancer types." (PMID 35480884, 2022). "The results of our analysis corroborate that CCNA2 is overexpressed in all 18 cancer types with enough normal tissues from the TCGA project." (PMID 35480884, 2022). "Cyclin A2 is an essential regulator of the cell division cycle and often found highly expressed in human cancers." (PMID 36561342, 2022). "CCNA2 overexpression has been reported in certain types of cancer, such as pancreatic ductal adenocarcinoma, stomach adenocarcinoma, and hepatocellular carcinoma." (PMID 35480884, 2022). "We found CCNA2 played a significant but contradictory role in immune infiltration in different cancer types." (PMID 35480884, 2022). "We employed TIMER2.0 to show the landscape of CCNA2 correlating with various immune infiltrates in different cancer types." (PMID 35480884, 2022). "CCNA2 overexpression has been observed in several types of cancers; also, a study has demonstrated that inhibition of CCNA2 led to the suppression of HCC, cell proliferation, and tumorigenesis." (PMID 36317111, 2022). "The expression level of CCNA2 is closely related with cell proliferation; thus, it is used as a proliferation marker for the molecular diagnosis of cancer." (PMID 34737951, 2021). "CCNA2 is highly expressed in several cancer cells and contributes to epithelial-mesenchymal transition through dual activation of WNT and PLC pathways." (PMID 34938346, 2021). "Our results show that cisplatin inhibited Ccna2 expression of Cyclin A2, which is normally expressed in dividing somatic cells to control the G1 to S transition as shown in our results with cancer mice." (PMID 34552585, 2021). "Increased expression of CCNA2 has been observed in various types of cancer such as lung, breast, liver, cervical, and others." (PMID 34737951, 2021). "Meanwhile, the expression of CCNA2 appears to be of prognostic value for the prediction of survival and early relapse in many types of cancer." (PMID 34737951, 2021). "CCNA2, which is one of the two A-type cyclins and ubiquitously expressed in cultured cells, has been reported to be upregulated in a variety of cancers." (PMID 34737951, 2021). "CCNA2 expression, moreover, is significantly upregulated in many cancer types according to the Human Protein Atlas database, implying its potential role in cancer development and progression." (PMID 33187219, 2020). "Data from the Human Protein Atlas show that CCNA2 is overexpressed in dozens of cancer types, suggesting a potential role in tumorigenesis." (PMID 32486290, 2020). "CCNA2, also known as CyclinA2, a highly conserved cyclin protein, has been found significantly over-expressed in various cancers." (PMID 32411535, 2020). "CCNA2 belongs to a highly conserved cyclin family and is up-regulated in dozens of cancer types, which indicates its potential roles in cancer transformation and progression." (PMID 30765611, 2019). "The overexpression of CDK1, TYMS, CDT1, and CCNA2 and the underexpression of PRKACB were associated with tumorigenesis, defective cell signaling, or aberrant metabolism in other cancers." (PMID 31205467, 2019). "CCNA2 upregulation is a promising therapeutic target in part because this gene is reported to interact with a number of available cancer drugs." (PMID 28145099, 2017). "With regard to the mechanism of action of the ObR antagonists, we showed that, in non-cancer HGrC1 cells, Lan1 and Lan2 decreased the expression of cyclin A2 and cdk4." (PMID 28861689, 2017). "Actually, there is a significant increase in the activity of the CCNA2 effector circuit as cancer stage progresses." (PMID 28042959, 2017).
cancer (continued). "Downregulation of CCNA2 in our study is consistent with the observation that overexpression of BRD2 upregulated the transcription of CCNA2 which led to aggressive cancer in the mouse." (PMID 26830473, 2016). "Collectively, our data indicate that GOS in combination with VPA overcomes the resistance of cancer cells to apoptosis at least partly by inducing cyclin A2 degradation and downregulating Akt signaling." (PMID 26517515, 2015). "Tylophorine enhances the c-Jun downregulation of the cyclin A2 promoter activity and results in carcinoma cells dominantly arrested at G1 phase for anti-cancer activity." (PMID 25669982, 2015). "Accordingly, the downstream pathway targets of c-Myc as well as those of cyclins D1 and D2 (e.g. pRb, cyclin A2 and cyclin B1) were also downregulated and contributed to the anti-cancer activity of tylophorine." (PMID 25669982, 2015). "Our data indicate that VPA, but not SAHA or tubacin, acts in synergy with GOS to induce apoptosis in these cancer cells by suppressing the cyclin-A2/Akt/FOXO3a signaling pathway." (PMID 26517515, 2015). "Our findings indicate that GOS and VPA co-treatment induces apoptosis in human cancer cells by suppressing the cyclin-A2/Akt/FOXO3a pathway." (PMID 26517515, 2015). "Taken together, these data indicated that GOS in combination with VPA induced the downregulation of cyclin A2, which was correlated with the decrease of Akt activity in cancer cells." (PMID 26517515, 2015). "For example, high c-Myc suppresses cancer metastasis, most likely through the direct transcriptional repression of integrin subunits, and cyclin A2 negatively controls cell motility by promoting RhoA activation and cytoskeletal rearrangements." (PMID 25360999, 2014). "These new data showed that both c-Myc and cyclin A2, two well-established proliferation markers, were able to inhibit cancer metastasis." (PMID 25360999, 2014). "KMT6 in mammalian cancer cells regulate genes that in turn control cell cycle progression such as Cyclin A2, D1 and E1." (PMID 25029110, 2014). "Provided the high expression of CCNA2 is involved in the development of tamoxifen resistance, how to manage cancer patients with CCNA2 overexpression remains a great challenge." (PMID 24622579, 2014). "CCNA2 (also known as CyclinA2) belongs to the highly conserved cyclin family and is significantly overexpressed in various cancer types." (PMID 24622579, 2014). "Data from Human Protein Atlas show that CCNA2 is overexpressed in dozens of cancer types, which indicates its potential roles in cancer transformation and progression." (PMID 24622579, 2014). "Cyclin A2 is involved in S phase and G2-M phase transition and is also over-expressed in various cancers." (PMID 24289849, 2013). "Cyclin A2 is a cell cycle control protein that plays an important role in cell proliferation and cancer." (PMID 23301056, 2013). "Our results shown that epigenetic expression of LEPREL1 inhibitS the cancer cell proliferation by arresting the G1/S phase via downregulation of cell cycle regulatory proteins, including Cyclin A2 and Cyclin E2." (PMID 24319452, 2013). "In the present study, we found that a reporter consisting of cyclin A2 fused to luciferase was responsive to S-phase-specific anti-cancer drug, HCPT in cellulo and in vivo." (PMID 23301056, 2013). "Cyclin A2, an originally identified A-type cyclin, is ubiquitously expressed in mitotically dividing cells and is upregulated in a variety of cancers." (PMID 22719783, 2012). "In the less differentiated and more aggressive PC-3, we observed the highest levels of E2F1, typical of aggressive cancer phenotype, and of its transcriptional-regulated target cyclin A2." (PMID 22095224, 2012). "As a new oncogenic gene, CCNA2 controls the growth and death of cancer cells." (PMID 39911278, 2025). "CCNA2 may increase resistance to chemotherapy, cancer metastases, relapse, and aggressive behavior in cancer." (PMID 39911278, 2025).